ADIG (adipogenin)
Description:
Key regulator of lipid storage that promotes the expansion of lipid droplets during the formation of mature adipocytes. Acts by forming a dodecameric complex with seipin (BSCL2) when adipocytes have differentiated and are undergoing maturation. In the dodecameric complex, ADIG antagonizes the activity of BSCL2 by reducing BSCL2-mediated triacylglycerol nucleation and relieving BSCL2's inhibition of GPAT3 and GPAT4. GPAT3 and GPAT4 then translocate to lipid droplets, promoting the synthesis of triacylglycerols and the expansion of lipid droplets.
Synonyms: MGC39724; SMAF1; RP5-1100H13.2
Tractability: Antibody: UniProt predicts a signal peptide or a membrane-spanning region.
Gene: Protein-coding gene on chromosome 20 (38,581,195 to 38,588,463, forward strand). Ensembl gene ENSG00000182035.
Subcellular location: Endoplasmic reticulum membrane
Gene Ontology:
Biological process: brown fat cell differentiation; lipid droplet formation; lipid storage; positive regulation of fat cell differentiation; white fat cell differentiation; fat cell differentiation
Cellular component: cytoplasm; endoplasmic reticulum membrane; lipid droplet; nucleus
Genetic constraint (gnomAD): Loss-of-function variants: 12 observed, 9.6 expected, observed/expected ratio (o/e) 1.25, 90% interval 0.79 to 1.85. That is too few expected variants to judge how well the gene tolerates losing a copy. Missense variants: 72 observed, 93.36 expected, observed/expected ratio (o/e) 0.77, 90% interval 0.64 to 0.94. Synonymous variants: 32 observed, 35.55 expected, observed/expected ratio (o/e) 0.9, 90% interval 0.68 to 1.21.
Homologues: Orthologues: chimpanzee ADIG (99% identical), macaque ADIG (94% identical), dog ADIG (86% identical), pig ADIG (81% identical), rat Adig (68% identical), mouse Adig (62% identical).
Diseases named in the same sentence as ADIG in open-access papers:
ADIG is named in the same sentence as 3 diseases in open-access papers, as found by Europe PMC text mining. Sharing a sentence is not in itself a finding about the gene and the disease.
ADIG shares sentences with these, for which no sentence is quoted: cancer (2 papers); infection (1); metabolic disease (1).